KRAS (KRas proto-oncogene, GTPase)
Diseases named in the same sentence as KRAS in open-access papers (continued):
Sharing a sentence is not in itself a finding about the gene and the disease.
pancreatic cancer (continued). "Since the status of KRAS have been studied in pure IPMN and NEN in multiple studies, we further searched COSMIC database for the information of the other two mutated genes (PCK1 and MLL3) in pancreatic neoplasms." (PMID 34801052, 2021). "Above, we found that ZNF154 hypermethylation in Illumina methylation array data (90.7%) was as frequent as KRAS mutations (90.7%) for the PAAD samples, making pancreatic cancer an interesting case study for comparing the utility of the two markers for classifying samples from blood." (PMID 33420235, 2021). "It has been demonstrated that KRAS mutation was present in the histologically negative surgical margins of 37 of 70 (53%) patients with pancreatic cancer." (PMID 34204940, 2021). "Furthermore, the ILK pathway was found to cross-talk with the KRAS pathway via a KRAS-ILK-hnRNPA1 regulatory loop in pancreatic cancer as well as in lung adenocarcinoma." (PMID 34233735, 2021). "Mutations in KRAS are the earliest events in pancreatic cancer initiation, and it is reported that expression of GSK-3b rises during progression of pancreatic cancer from preneoplastic lesions, suggesting a possible role for this oncogene in the observed overexpression." (PMID 34955846, 2021). "FOSL1 inhibition is detrimental to both KRAS-driven lung and pancreatic cancer." (PMID 34503105, 2021). "The KRAS/Lin28B axis maintains stemness of pancreatic cancer cells via the let‐7i/TET3 pathway." (PMID 33107691, 2021). "The level of miR-193b, which targets KRAS, is downregulated in pancreatic cancer." (PMID 33435156, 2021). "Of note, artesunate triggered ferroptosis in a most efficient way in pancreatic cancer cells carrying mutationally-active KRas mutations (i.e., AsPC-1) rather than in pancreatic cancer cells expressing wild type KRas (i.e., COLO-357 and BxPC-3)." (PMID 33467668, 2021). "Indeed, it has been shown that oncogenic KRAS downregulates hormone-sensitive lipase (HSL) in pancreatic cancer, modulating invasion and metastasis." (PMID 34485382, 2021). "The KRAS mutation follows the loss of PTEN (phosphatase and tensin homolog), a tumor suppressor that inhibits the activation of the PI3K/Akt pathway, which is hyperactivated in 60% of pancreatic cancer cases." (PMID 34354940, 2021). "However, in the case of KRAS mutant cancer, the effect of KRAS depletion results in the variable induction of apoptosis, highlighted in KRAS mutant lung and pancreatic cancer cell lines." (PMID 34680229, 2021). "Thus, if KRAS is mutated in pancreatic cancer cells, inflammatory signals cause further secretion of cytokines and also lead to dysregulated activation of STAT3 as positive feedback, fueling KRAS-driven pancreatic cancer." (PMID 33801246, 2021). "Importantly, such activation was validated in vivo, when comparing KRASG12D/+ pancreatic cancer cells to KRASLSL/+ epithelial cells in murine KRAS PanIN and PDA." (PMID 34485382, 2021). "Moreover, miR-96 is known as a tumor suppressor in pancreatic cancer by suppressing KRAS, as well as in endometrial and breast cancers by suppressing FoxO1 and FOXO3 genes." (PMID 33788050, 2021). "Therefore, our results illuminate the distinct mechanism of Lin28B nuclear translocation and suggest that the KRAS/Lin28B axis drives the let‐7i/TET3 pathway to maintain the stemness of pancreatic cancer cells." (PMID 33107691, 2021).
pancreatic cancer (continued). "Thus, in this study, we investigated both the expression and the role of HPS in KRAS-mutated PDAC cell lines, and we analyzed lipidomic differences, including n-3 and n-6 PUFAs, in HPS-knockdown pancreatic cancer cells." (PMID 33801246, 2021). "However, given the long latency until development of invasive PDAC the impact of p200 CUX1 in this KRAS-driven pancreatic cancer model appeared to be rather modest." (PMID 34070180, 2021). "In addition, GEM ExTra identified KRAS alterations in approximately 77% of pancreatic tumors which generally correlates with previous estimates in this tumor type." (PMID 33889297, 2021). "Moreover, KS-58 is the first KRAS-G12D inhibitor and, so far, it has been tested in preclinical trials in lung and pancreatic cancer, showing promising results." (PMID 34359657, 2021). "Although KRAS G12C mutations are not as frequent in pancreatic cancer, these results collectively provide hope for the development of other similar therapeutics targeting the more commonly observed KRAS G12D and G12V mutations." (PMID 33546207, 2021). "ALK rearrangement-positive is rare in pancreatic cancer, but may occur in those with KRAS-wild type." (PMID 34568053, 2021). "Analogously to what we have recently published for conglobatin A, elaiophylin may have a high efficacy in KRAS mutant cancers with high HIF1α and Gal3 levels, which is particularly the case in pancreatic cancer." (PMID 34199986, 2021). "In this regard, inhibition of the ERK/MAPK (mitogen-activated protein kinase) signaling downstream of KRAS in pancreatic cancer cells elicits autophagy as a survival response, in order to protect pancreatic cancer cells from the cytotoxic effects of ERK signaling inhibition." (PMID 34885233, 2021). "For these reasons, we decided to conduct a head-to-head comparison of ZNF154 hypermethylation versus KRAS mutation for classifying plasma samples taken from individuals with and without pancreatic cancer." (PMID 33420235, 2021). "In addition, knockdown of STK33 in KRAS mutant epithelial cancer cell lines from different origins (including colorectal, breast, and pancreatic cancers) led to impaired colony formation in vitro and slower growth in vivo." (PMID 34955846, 2021). "Based on our in vitro and in vivo data, the CUX1–EGF–MEK-ERK circuit might represent a promising target for therapeutic intervention to target KRAS-driven pancreatic cancer." (PMID 34070180, 2021). "Therefore, our result implies that KRAS/p-STAT3 mediates the regulation of HPS expression in SUIT-2 pancreatic cancer cells." (PMID 33801246, 2021). "In conclusion, this study clarified that invasion of pancreatic cancer cells is promoted by ARL4C, of which expression is induced by KRAS and Wnt signaling, and that association of ARL4C with IQGAP1 and MMP14 at the tips of invasive pseudopods are essential for the invasive ability." (PMID 34590580, 2021). "It is suggested that Lin28B plays a key role in KRAS‐driven pancreatic cancer." (PMID 33107691, 2021). "KRAS mutations mainly occur at codons 12, 13 and 61, and the G12C mutation is the most common (41%) in NSCLC, whereas the KRAS G12D and G12V mutations are the major subtypes in colorectal and pancreatic cancers." (PMID 34885068, 2021).
pancreatic cancer (continued). "This question has potential translational relevance, given that there is no clinically proven treatment for most tumors with mutant KRAS, although it has been known for many years that it is commonly mutated in pancreatic cancer, LUAD, and colorectal cancer." (PMID 34862367, 2021). "YAP1 has been shown to overcome KRAS blockade to prompt pancreatic cancer growth in murine models." (PMID 33777798, 2021). "Among these are the KRAS peptide vaccines for the treatment of pancreatic cancer." (PMID 34771675, 2021). "Drugs that target some of these other proteins could be more effective at treating pancreatic cancer than the drugs that target KRAS." (PMID 34590580, 2021). "CRISPR systems are being used to target KRAS in pancreatic cancer." (PMID 34781949, 2021). "Thus, the aim of this study was to study the regulatory mechanism of miRNA and lncRNA upstream of KRAS in exosomes derived from pancreatic cancer MSCs." (PMID 33643376, 2021). "In addition to promoting macrophage M2 polarization, IL-4, which is abundantly produced by TH2 cells, has been recently demonstrated to stimulate tumor cell proliferation through KRAS in pancreatic cancer." (PMID 33777798, 2021). "In addition, leukemia inhibitory factor (LIF) inhibits the activity of the Hippo-signaling pathway and subsequently increases YAP transcriptional activity in KRAS-driven pancreatic cancer." (PMID 33408779, 2021). "Of note, TXN is dysregulated in pancreatic cancer where it regulates KRAS signaling pathway, indicating that it may represent a good strategy to induce ferroptosis in RAS-driven cancers." (PMID 34485382, 2021). "KRAS mutations are typically mutually exclusive, with recurrent activating mutations (KRAS (Gly 12) and KRAS (Gly 13) common in colon cancer, non-small cell lung cancer and pancreatic cancer." (PMID 34302033, 2021). "The panel tested for the presence cfDNA KRAS mutations and serum levels of CA19-9, CEA, HGF and OPN—protein markers that are used clinically to follow pancreatic cancer patient treatment course or have been previously found to be dysregulated in pancreatic cancer patients." (PMID 34968245, 2021). "Thus, this new study reveals that syndecan-1 plays a crucial role in macropinocytosis in KRAS-driven pancreatic cancer." (PMID 33669066, 2021). "Most studies have assayed KRAS oncogene mutations to identify circulating tumor DNA (ctDNA), and several groups, including ours, have reported that the presence of a KRAS mutation has a negative influence on the prognosis of pancreatic cancer patients." (PMID 34771630, 2021). "Indeed, blocking the KRAS–HSL axis lowers lipid storage into lipid droplets, effectively reducing invasive capacity of KRAS-mutant pancreatic cancer." (PMID 34485382, 2021). "While most of the G4-related studies in the context of pancreatic cancer focus on changes of KRAS expression, one study demonstrated that G4 stabilization by BMSG-SH-3 in MIA Pa-Ca-2 xenograft tumors led to telomere shortening caused by reduced expression of TERT." (PMID 33632214, 2021). "Pancreatic cancers without KRAS mutations (about 10% of PDAC) show wild type RAS activation via upstream signaling through receptor tyrosine kinases, including epidermal growth factor receptor (EGFR), which is also required in KRASG12D-driven PDAC." (PMID 34680275, 2021). "It has been demonstrated that mutant KRAS pancreatic cancer cell lines treated with chemotherapy activate MAPK and NF-κB pathways, inducing the secretion of inflammatory cytokines able to enhance monocyte differentiation towards MDSCs and thus counteracting therapy response." (PMID 33777798, 2021).
pancreatic cancer (continued). "In addition to ctDNA, exoDNA has also been shown to have prognostic value, with KRAS mutant allele fraction (MAF) being associated with progression-free survival (PFS) and overall-survival (OS) in pancreatic cancer." (PMID 33673461, 2021). "In mRNA level, according to TCGA datasets, pancreatic cancer samples which harbored mutant KRAS have a higher level of HSF1 compared to no mutation samples." (PMID 33422093, 2021). "It has been previously reported that STAT3 phosphorylation is a critical early event in the formation of precursor lesions for pancreatic cancer, and the conditional deletion of the Stat3 gene in mice expressing mutant KRAS in the pancreas blocked the development of PanINs." (PMID 34491463, 2021). "KRAS G12R is most commonly seen in pancreatic tumors versus other tumors of humans (15%)." (PMID 34901697, 2021). "Due to this fact, studying the function of KRAS and the impact of its mutations on the tumor microenvironment (TME) is a priority for understanding pancreatic cancer progression and designing novel therapeutic strategies for the treatment of the dismal disease." (PMID 34638560, 2021). "Whereas KRAS is mutated in most pancreatic cancer patients, controlling KRAS or its downstream effectors has not been succeeded clinically." (PMID 34590580, 2021). "Despite the discouraging results of FNA, after DNA amplification, KRAS mutation was detected in none of the AIP cases but in 10/11 of the pancreatic cancer cases." (PMID 34573995, 2021). "In the same study, KRAS mutant and dependent pancreatic cancer lines also exhibited over 8,000 differential methylations of CpGs upon KRAS knockdown and differentially methylated promoters also showed an enrichment of genes involved in differentiation and development." (PMID 34805167, 2021). "In this progenitor state, KRas activates inflammatory pathways to initiate pancreatic cancer." (PMID 33669845, 2021). "Thus, mutant KRAS plays a major role in TAZ expression and cancer stem self-renewal in pancreatic cancer cells, and ICMT has potential as a pharmacological target in the treatment of mutant KRAS pancreatic cancer cells." (PMID 34395269, 2021). "Such an approach is employed in an ongoing phase II trial (NCT01676259), where patients with pancreatic cancer receive intratumoural injection of a KRAS-G12D-specific siRNA in a biodegradable matrix (allowing prolonged drug release) in combination with systemic chemotherapy." (PMID 34200676, 2021). "This may be of particular relevance to pancreatic tumors that highly depend on both mutant KRAS signaling and heightened SOCE." (PMID 33919156, 2021). "Regardless the similarities and differences in the phenotype and genetic background of the PDAC cell lines used in our studies, these results validate our previous findings in an in vivo setting and indicate that MRP4 levels determine pancreatic tumor development, independently of KRAS status." (PMID 32848164, 2020). "Indeed, a prior study suggested that overexpression of a single ETS TF confers resistance to MEKi trametinib in KRAS mutant pancreatic cancer, while suppression of ETV1, ETV4, or ETV5 alone strongly decreased the resistance." (PMID 32413516, 2020).
pancreatic cancer (continued). "A recent study suggests that methylation on arginine 248 inhibits MDH1 catalytic activity and dimerization by coactivator-associated arginine methyltransferase 1 (CARM1), and KRAS suppresses CARM1-mediated MDH1 methylation, contributing to glutamine metabolism in pancreatic cancer." (PMID 33117704, 2020). "Altogether, these data show that the E2F1-EP300 activator/co-activator complex is part of the novel signaling pathway controlling the promoter activity and, consequently, the expression of the autophagy-related gene VMP1 in pancreatic tumor cells carrying oncogenic KRAS." (PMID 32655498, 2020). "Notably, other members of the Argonaute family fail to compensate for these functions, reiterating the specific role of AGO2 in KRAS-driven pancreatic cancer." (PMID 32499547, 2020). "However, we did identify novel changes in genes related to development and differentiation after KRAS silencing, which was common to all our pancreatic cancer cell lines but was more pronounced in the KRAS-responsive lines." (PMID 32576853, 2020). "KRAS is the most commonly mutated gene in pancreatic cancer, but clinical agents that directly target mutant KRAS are not available." (PMID 32636409, 2020). "Homologous recombination repair deficiency is one of the hallmarks of a subset of pancreatic cancer, and mutations of DNA repair genes (BRCA1/2, CHECK2, ATM, PALB2) may occur together with KRAS (20%)." (PMID 32725342, 2020). "We found that 4799 genes were differentially expressed in pancreatic cancer patients with or without KRAS mutation." (PMID 32950968, 2020). "As discussed here, KRAS-wild type PDAC may represent a distinct molecular subtype of pancreatic cancer." (PMID 33115526, 2020). "Moreover, the mutant KRAS/galectin-3/αvβ3 complex also maintains the redox balance of pancreatic cancer cells." (PMID 32122374, 2020). "Consequently, activating mutations of KRAS and BRAF produce at last the activation of this pathway, which is crucial for pancreatic cancer." (PMID 33115526, 2020). "According to existing data, among the markers identified in the stool that may contribute to the early diagnosis of pancreatic cancer are the mutant KRAS gene and methylated BMP3." (PMID 33114412, 2020). "It has been reported that dasatinib enhances the inhibitory effect of tumor cell growth by trametinib, a mitogen-activated protein kinase kinase inhibitor, in vitro and in vivo in various KRAS-mutant cancer cells, including lung, breast, colon, and pancreatic cancer cells." (PMID 32171300, 2020). "KRAS mutation and CDKN2A deletion are occurred in the initiating stage of pancreatic cancer." (PMID 32950968, 2020). "Although KRAS mutations are predominant in pancreatic cancer, no effective therapeutic agent targeting KRAS mutations has been discovered until date." (PMID 31997007, 2020). "In pancreatic cancer, the salivary messenger RNA can be used to detect KRAS, Methyl-CpG Binding Domain Protein 3-Like 2 (MBD3L2), Acrosomal Vesicle Protein 1 (ACRV1) and Dolichyl-Phosphate Mannosyltransferase Subunit 1 (DPM1) with 90% sensitivity and 95% specificity." (PMID 32294884, 2020). "As KRAS and BRAF mutations are prevalent in CRC, NRF2 may frequently be upregulated by transcriptional activation of NFE2L2, as reported in mouse models of pancreatic cancer." (PMID 33276631, 2020). "While miR-200c-3p and miR-217 induce MALAT1 RNA degradation, MALAT1 suppresses miR-200c-3p and miR-217 function and miR-217 translocation from the nucleus to the cytoplasm, up-regulates ZEB1 and KRAS expression, and induces pancreatic cancer cell migration and invasion." (PMID 32174966, 2020). "On the other hand, pancreatic cancers with wild-type KRAS, although rare, account for only about 5% of all cases; BRAF and EGFR gene mutations and some fusion genes (FGFR, ALK, NTRK, NRG1, etc.)have also been reported to be detected at a relatively high frequency." (PMID 31997007, 2020).